CCNB1 (cyclin B1)
Diseases named in the same sentence as CCNB1 in open-access papers (continued):
Sharing a sentence is not in itself a finding about the gene and the disease.
tumor (continued). "The identified targets of miR-93 include P21, cyclin B1 (CCNB1), ERBB2, Akt3, SOX4, STAT3, vascular endothelial growth factor A (VEGFA), and Smad7, suggesting that miR-93 may play tumor suppressor roles through diverse mechanisms." (PMID 25649143, 2015). "Using a combined geneset of these 5 remaining cell cycle-related genes (BUB1B, CCNB1, CCNB2, TTK and CDK1) as well as ADAM7 and FAM72B, we also observed a statistically-significant reduction in disease-free survival of patients with tumours exhibiting alterations in gene expression (p = 0.015)." (PMID 25519703, 2014). "Three (caveolin-1, cyclin B1 and Src-pY527) of four marker signature that differentiates NSCLC from normal lung in Nanjundan's study were also significantly different between normal and tumor tissues of the current studies." (PMID 22348039, 2012). "Only a portion of tumor cells were stained strongly with cyclin B1 antibody whereas other tumor cells in the same tumor showed very low or negative staining for cyclin B1, possibly because of different status of cell cycles." (PMID 22348039, 2012). "The tumor samples were isolated, cells were harvested, and experiments were conducted to test whether 6-OAP induced mitotic arrest and perturbed cyclin B1 expression in vivo." (PMID 21755010, 2011). "UBE2C, CCNB1, CCNB2, PLOD2, NUP210, MELK, CDC20 genes were overexpressed in tumours and in CIN3/CIS relative to both Normal and CIN1/CIN2, suggesting that they could have a role to play in the early phase of tumorigenesis." (PMID 21338529, 2011). "UBE2C, CCNB1, CCNB2, PLOD2, NUP210, MELK, CDC20 were overexpressed in tumours and in CIN3/CIS relative to both Normal and CIN1/CIN2, suggesting that they could have an important role to play in the early phase of tumorigenesis." (PMID 21338529, 2011). "Peptides derived from over expressed (Telomerase, Survivin, and Cyclin B1), differentiation (MART-1) and cancer testis antigens (NY-ESO-1) served as known targets, while autologous tumor cell lines presented a panel of unknown antigen specificities." (PMID 21773037, 2011). "The expected model size with the highest performance level consists of 10 of the most robust predictive variables and is comprised of four clinico-pathological variables and six additional proteins: nodal status, tumor size, AURKA, BCL2, age, CD68, HER2, MYBL2, CCNB1 and GSTM1." (PMID 20809974, 2010). "Additionally, the expression level of the CCNB1 gene, a prominent oncogene, was significantly increased in tumor tissues compared to non-tumor margin tissues (3.97-fold, p < 0.0001)." (PMID 41568058, 2026). "Meanwhile, we observed a significant overlap in the expression patterns of key cell cycle regulators, including CDC25C, CCNB1, and CDK1, with PPIH in malignant cells, further suggesting that PPIH may promote tumor cell proliferation by modulating cell cycle progression." (PMID 40895540, 2025). "Because cyclin B1 is expressed in the G2/M transition and is essential for the initiation of mitosis, it is not surprising that CCNB1 expression may be indicative of tumor proliferation." (PMID 38095839, 2024). "Regardless of whether MDR (tumor) or normal tissue (liver) was used, we observed a decrease in Cyclin B1 with M2I-1 treatment." (PMID 38730707, 2024). "Western blotting results showed that the protein levels of cell cycle-related proteins cyclin B1, cyclin D, and anti-apoptotic protein Bcl-2 had decreased, while the apoptosis-related protein Bak had increased both in NSCLC cells and in A549-xenografted tumor tissues." (PMID 38287075, 2024). "The interaction network showed that FOXM1 was closely correlated with those proteins who are involved in the cell cycle, such as cyclin-dependent kinase 1 (CDK1), CDK2, Cyclin B1 (CCNB1), as well as CCNB2, indicating FOXM1 may act as an important regulator of the tumor cell cycle." (PMID 37159818, 2023).
tumor (continued). "On the other hand, TIS21/BTG2/PC3 can inhibit the degradation of cyclin A and cyclin B1 in G2/M phase when stimulated by epidermal growth factor (EGF) at high concentration, and directly combine with Cdc2, thus hindering cell mitosis and increasing the aging and death of tumor cells." (PMID 37794858, 2023). "As a result of the proliferation induced by tumour cells, when CCNB1 is highly expressed in a malignant cell, the cell may not be stable in the long term, leading to variation between mRNA and protein levels." (PMID 36418517, 2023). "We found that FOXM1a overexpression significantly decreased the expression of CDC25B, PLK1, and CCNB1 in both CAL 27 and SCC-9 cells, indicating that FOXM1a may inhibit cell proliferation and tumor formation through downregulating the expression of these key genes." (PMID 37759731, 2023). "BHE inhibits the cyclin B1/cDC2 signaling pathways to achieve antitumor effects, which demonstrates its great potential as a new anticancer drug for the treatment of patients with HCC and provides a theoretical basis for the further development and utilization of blue honeysuckle in tumor therapy." (PMID 36212967, 2022). "However, BUB1, CCNB1, BUB1B, KIF11, CDC20, TTK, and NCAPG, which are closely related to regulation of the cell cycle and DNA repair, showed strong positive correlations with tumor purity in luminal-type BC." (PMID 34733851, 2021). "Moreover, overexpression of CDK1, CCNB1, CDC20, BUB1, MAD2L1, and BUB1B in tumour tissues could increase cell proliferation and division." (PMID 33035258, 2020). "In high PPS20 group, we found increased protein level expression of Cyclin B1, which is a marker of cell proliferation and as well as DNA repair which is consistent with increased RAD51 which is involved in double stranded break repair, tumor progression and resistance to anti-cancer treatments." (PMID 32310997, 2020). "S100A4, cathepsin B, cyclin B1, Annexin A2, S100A10, TRIM21, 14-3-3 ζ/δ, and Ezrin may hence participate in tumor invasion depending on the grade of human CRCs, and protein upregulation during lymph node metastasis also suggests a positive correlation with metastasis in human CRCs." (PMID 32154176, 2020). "Il6 deficiency also reduced hepatic mRNA levels of Stat3 target genes (Birc5, Bcl2l1 and Ccnd1), cyclins (Ccna2, Ccnb1, Ccnb2), and markers of proliferation (Mki67) and HCC (Afp) in livers from FGF19-expressing mice, further demonstrating the role of IL-6 in mediating FGF19-driven tumour growth." (PMID 28508871, 2017). "The present analysis showed, for the first time, that the anti-tumor effect of fisetin was mediated mainly through modulation of multiple signaling pathways and via activation of CDKN1A, SEMA3E, GADD45B and GADD45A and down-regulation of TOP2A, KIF20A, CCNB2 and CCNB1 genes." (PMID 28052097, 2017). "GEP studies have consistently identified at least two groups of ER+ tumours; the less favourable LB group being characterised by higher histological grade and higher expression of proliferation and HER2-related genes, such as MKI67, MYBBL2, CCNB1, HER2 and GRB7, and lower levels of ER-related genes." (PMID 21712826, 2011). "This implies cyclin B1 expression may not be a pure proliferation marker but reflects also other features, for exqample, genomic instability of the tumour as suggested by previous studies." (PMID 19293801, 2009).
tumor (continued). "Additionally, analysis of BUB1 mRNA expression in the TCGA MPM dataset—as an indicator of tumor cell proliferation—revealed a strong positive correlation between BUB1 expression and well-established proliferation and cell cycle markers, Ki67, PCNA, CCNB1, and CDC20." (PMID 40180891, 2025). "However, the lack of a significant correlation with tumor grade indicates that CCNB1 may be more critical in the context of tumor invasion rather than differentiation." (PMID 39795587, 2024). "As HOXD9 is an important transcription factor promoting tumor proliferation, we examined the correlation between HOXD9 mRNA levels and proliferation markers PCNA, Ki-67 as well as cell cycle related genes CCNA2 and CCNB1 to validate whether HOXD9 can facilitate ATC proliferation." (PMID 37974228, 2023). "Furthermore, as the tumor status changed with treatment, the expression levels of these genes changed correspondingly in PBMCs; treated HCC patients without active/residual tumor cells had higher transcript levels of CCNB1, CDC20, and CENPF compared with the other two subgroups of HCC patients." (PMID 34660300, 2021). "Cyclin B1 could not be detected in the tumor tissue of the PPP-treated A549 xenografts." (PMID 25268741, 2014). "Moreover, the mRNA of several cell cycle regulatory genes, such as Cdc25b, Cyclin B1, Cyclin A2, Plk1, Cks1, Aurora B, and Topo 2 alpha were decreased in prostates of TRAMP/SPDEF OE mice, a finding consistent with decreased cellular proliferation and decreased tumor sizes." (PMID 25254494, 2014). "Further analysis of the model genes within MOCM across pan‐cancer settings revealed that ANLN, CCNB1, CDKN3, EXO1, GJB3 and RAD51AP1 were predominantly overexpressed in tumour tissues, while GGT6 and CYP4B1 were highly expressed in normal tissues." (PMID 38958523, 2024). "In the Nottingham cohort, Cox regression analysis showed that high expression of CCNB1 was a significant predictor of shorter BCSS regardless of LVI status, tumour size, LN stage and tumour grade (HR = 1.3; 95% CI 1.1–1.5;p = 0.010)." (PMID 36418517, 2023). "To further verify the results of bioinformatics analysis, we applied qRT-PCR to validate the mRNA levels of HMMR, SPP1, FN1, CCNB1, CXCL8, MAD2L1 and CCNA2 in 10 paired tumor and adjacent normal tissues with qRT-PCR." (PMID 34126961, 2021). "There is no staining of TTK, CCNB1, and CCNB2 in normal human lung tissues; however TTK, CCNB1, and CCNB2 showed strong positive in NSCLC tissues; the majority of positive cells were tumor cells and immune cells." (PMID 32969465, 2020). "Tumors having both positive and negative tumor areas for cytoplasmic BUB3 (30%), CCNB1 (28%), or PTTG1 (35%) were considered heterogeneous." (PMID 31801961, 2020). "Our analysis revealed that the expression patterns of AURKB, CCNB1, PLK1, and USP7 were all higher in tumor tissues than in normal tissues, although their basal levels were different in each cancer." (PMID 33207738, 2020). "The relative expressions of CCNB1, CCNB2, and CHEK1 mRNA were 3.938±3.887-, 3.225±3.388-, and 3.186±3.508-fold upregulated in 20 tumor tissues versus adjacent nontumor tissues, respectively." (PMID 30228980, 2018). "Additionally, under low dietary methionine conditions, NR4A2 abrogation did not further impede ESCC tumor growth and decline intratumoral expression of PCNA and Cyclin B1." (PMID 38570607, 2024).
tumor (continued). "Regardless of the classification standards (TNM staging/Histology Grade/Vascular invasion) used for analysis, all results revealed that CCNB1, CDC20, and CENPF were already significantly upregulated in the early stages of HCC tumor tissues (T1/G1/Stage I/no vascular invasion)." (PMID 34660300, 2021). "However, the fascinating observation of our study is that the hub genes including CDK1, CDK2, CCNB1, and HDAC1 and common genes including E2F3 identified in Rb tissues are well-known oncogenes that trigger cell cycle progression in tumor cells in the absence of RB1 gene." (PMID 35359459, 2022).
cancer (491 papers, 2008 to 2026). A tumor composed of atypical neoplastic, often pleomorphic cells that invade other tissues. "The affected proliferation of cancer cells was associated with the down‐regulated cell cycle proteins, Cyclin B1 and CDK1." (PMID 40635123, 2025). "CCNB1 dysregulation represents an early tumorigenic event, with its expression patterns intricately linked to cancer progression." (PMID 41614789, 2025). "To assess the association between the expression of CCNB1 and clinico-pathological features in multiple cancers, we first analyzed the CCNB1 expression at different clinical stages of cancer using the Sangerbox database." (PMID 38581717, 2024). "High expression of CDK1 and Cyclin B1 and low levels of p21/p27 are frequently detected in various types of cancer and associated with cancer development and poor prognosis." (PMID 38789954, 2024). "Our study is the first to demonstrate a potential association between CCNB1 mRNA expression and immune infiltration across various cancers." (PMID 38581717, 2024). "We finally explored potential binding proteins and genes associated with CCNB1 expression across the different cancer types." (PMID 38581717, 2024). "Our research revealed an association between CCNB1 upregulation and progression through clinical stages across various cancers." (PMID 38581717, 2024). "Further, the GEPIA 2.0 web tool facilitated the identification of the top 100 genes associated with CCNB1 across all cancer tissues from the TCGA database." (PMID 38581717, 2024). "To elucidate the mutation landscape of CCNB1 across protein domains in pan-cancer, we identified a total of 59 mutation sites ranging from amino acid positions 0–433." (PMID 38581717, 2024). "High expression of Cyclin B1 and low levels of p21/p27 are frequently detected in various types of cancer and associated with cancer development and poor prognosis." (PMID 38755221, 2024). "The expression of CCNB1 is associated with clinicopathological stages, prognosis, immune cell infiltration, and immune-related genes in most cancer types." (PMID 38581717, 2024). "To validate the potential regulatory function of NQO1 in cell cycle progression at the G2/M phase in cancer cells, we determined the protein levels of associated cyclin B1 and CDK1." (PMID 36793872, 2023). "In other cancers, inhibition of cell cycle progression was shown to be caused by the reduction of CCNB1 and CDK1 expression induced by the inhibition of HSP90." (PMID 37547755, 2023). "In our observations, SFN treatment of cancer cells led to the decrease of cyclin B1/CDC2 complex association and phosphorylation of CDC25C." (PMID 37189614, 2023). "Aberrant levels of the G2/M cyclin cyclin B1 (gene CCNB1) have been associated with multiple cancers; however, the literature lacks a focused and comprehensive analysis of the regulation of this important regulator of cell proliferation in cancer." (PMID 37758792, 2023). "For example, quercetin halts the cell cycle at the G2/M phase by raising Cdk‐inhibitor, especially p21CIP1/WAF1 and its associated protein Cdc2‐cyclin B1 complex in MCF‐7 cancer cells." (PMID 37132286, 2023). "The overexpression of cyclin B1 is associated with transformed cells and is a marker of poor prognosis for a variety of cancers." (PMID 36230831, 2022). "Overexpression of CCNB1 was associated with various cancer types, and predicted inferior response to mTOR inhibitor." (PMID 34051812, 2021). "Previous studies investigating the process of cell cycle regulation in cancer cells have shown that loss of cyclin B1 function in cells directly results in downregulation of cyclin A and CDK2, leading to cell cycle arrest and induction of apoptosis." (PMID 34685613, 2021). "aAbs against some other frequently mutated proteins in cancer that have a role in cell cycle, such as c-myc and cyclin B1, are also found in some patients with solid cancers, including ovarian and lung cancer." (PMID 34360795, 2021).